LINC01206 (long independently transcribed non-coding RNA 1206)
Gene: Long non-coding RNA gene on chromosome 3 (181,952,343 to 182,052,270, forward strand). Ensembl gene ENSG00000242512.
Diseases named in the same sentence as LINC01206 in open-access papers:
LINC01206 is named in the same sentence as 7 diseases in open-access papers, as found by Europe PMC text mining. Sharing a sentence is not in itself a finding about the gene and the disease. The quoted sentences say what the papers report.
psoriasis (1 paper, 2025). An autoimmune condition characterized by red, well-delineated plaques with silvery scales that are usually on the extensor surfaces and scalp. "To further elucidate the role of LINC01206 in psoriasis, we examined its expression in psoriatic lesions and IL‐17A‐stimulated NHEK cells." (PMID 40670887, 2025). "By regulating EHF and its downstream targets, LINC01206 emerges as a key player in psoriasis pathogenesis and a potential therapeutic target for future interventions." (PMID 40670887, 2025). "Our findings suggest that LINC01206 enhances keratinocyte proliferation in psoriasis by regulating cell cycle progression, making it a potential therapeutic target for psoriasis treatment." (PMID 40670887, 2025). "IL‐17A is a primary driver of skin pathology in psoriasis, and our results showed that LINC01206 expression is significantly upregulated in both psoriatic lesions and IL‐17A‐stimulated keratinocytes." (PMID 40670887, 2025). "This study investigates the role of lncRNAs, particularly LINC01206, in psoriasis pathogenesis, focusing on their involvement in cell cycle regulation." (PMID 40670887, 2025). "In conclusion, this study enhances our understanding of the role of LINC01206 in psoriasis by demonstrating its involvement in cell cycle regulation and keratinocyte hyperproliferation." (PMID 40670887, 2025). "This regulatory circuit was experimentally validated in normal human epidermal keratinocytes (NHEK), highlighting the critical role of LINC01206 in psoriasis pathogenesis through its interaction with EHF and cell cycle genes." (PMID 40670887, 2025). "Through bioinformatics analysis and experimental validation, we demonstrate that LINC01206 plays a pivotal role in psoriasis by modulating cell cycle progression, offering new insights into the disease's molecular mechanisms and potential therapeutic targets." (PMID 40670887, 2025). "QPCR analysis revealed that knockdown of LINC01206 led to increased expression of hyperproliferation markers KRT6, KRT16, and KRT17, suggesting that LINC01206 may promote aberrant keratinocyte proliferation in psoriasis." (PMID 40670887, 2025). "Finally, although our focus was on cell cycle regulation, the multifactorial nature of psoriasis suggests that LINC01206 may influence other cellular processes and signalling pathways, warranting further exploration." (PMID 40670887, 2025). "Co‐expression analysis revealed a strong correlation between LINC01206 and EHF in psoriasis, suggesting their functional interaction." (PMID 40670887, 2025). "As expected, LINC01206 expression was significantly upregulated in NHEK cells following IL‐17A stimulation, consistent with its expression pattern in clinical psoriasis samples." (PMID 40670887, 2025).
Stroke (1 paper, 2023). Sudden impairment of blood flow to a part of the brain due to occlusion or rupture of an artery to the brain. "Non-coding genes LINC00870, LINC01206, LINC01287, and LINC02073 are mainly more highly expressed in stroke patients, so they are upregulated." (PMID 37508918, 2023).
LINC01206 also shares sentences with these, for which no sentence is quoted: cancer (1 paper); dengue (1); hepatocellular carcinoma (1); squamous cell carcinoma of the lung (1); triple-negative breast carcinoma (1).